AGTR2 (angiotensin II receptor type 2)
Diseases named in the same sentence as AGTR2 in open-access papers (continued):
Sharing a sentence is not in itself a finding about the gene and the disease.
renal disease (4 papers, 2014 to 2023). "The three remaining RAAS genes included in this meta-analysis, ACE2, AGTR2 and REN, have not been researched as extensively as ACE, AGT and AGTR1 for associations with renal disease." (PMID 31048445, 2019).
adenocarcinoma (2 papers, 2017 to 2020). A common cancer characterized by the presence of malignant glandular cells. "Notably, AGTR2, which encodes the AT2 angiotensin II receptor subtype, was significantly underexpressed in adenocarcinoma tissue (p < 0.01)." (PMID 28791183, 2017).
psychiatric disorder (1 paper, 2023). A disorder characterized by behavioral and/or psychological abnormalities, often accompanied by physical symptoms. "Nevertheless, we detected four inherited rare variants of unknown significance in four respective genes implicated in psychiatric disorders in the patient, including p.Arg1627Trp of LAMA2, p.Arg691Gly of TLR4, p.Pro1338Ser of CSMD1, and Arg182X of AGTR2." (PMID 37511534, 2023).
urological disorders (1 paper, 2007). "Conversely, angiotensin II type 2 receptor (AGTR2) null mutant mice have urological disorders, including both obstructive anomalies and reflux, with or without renal hypo/dysplasia." (PMID 17216254, 2007).
AGTR2 also shares sentences with these, for which no sentence is quoted: atherosclerosis (6 papers); Alzheimer disease (5); breast carcinoma (4); Parkinson disease (4); cognitive decline (3); endothelial dysfunction (3); ischemia (3); ischemic stroke (3); lung carcinoma (3); metabolic disorders (3); Myocardial fibrosis (3); myocardial infarction (3); Sepsis (3); Arthritis (2); Cerebral ischemia (2); colorectal (2); glioma (2); kidney damage (2); neurodegenerative disease (2); neurological disorders (2); pituitary adenoma (2); renal fibrosis (2); type 1 diabetes (2); abdominal aortic aneurysm (1); acute myocardial infarction (1); acute renal failure (1); adenocarcinoma of prostate (1); adenoma (1); anaphylaxis (1); anemia (1).
A further 59 diseases each share a sentence with AGTR2 in 1 paper.